H2BC18 (H2B clustered histone 18)
Description:
Core component of nucleosome. Nucleosomes wrap and compact DNA into chromatin, limiting DNA accessibility to the cellular machineries which require DNA as a template. Histones thereby play a central role in transcription regulation, DNA repair, DNA replication and chromosomal stability. DNA accessibility is regulated via a complex set of post-translational modifications of histones, also called histone code, and nucleosome remodeling.
Synonyms: HIST2H2BF
Tractability: PROTAC: UniProt records ubiquitination sites on it; ubiquitination databases record sites on it.
Gene: Protein-coding gene on chromosome 1 (149,782,689 to 149,812,373, reverse strand). Ensembl gene ENSG00000203814.
Subcellular location: Nucleus; Chromosome
Subcellular location (Human Protein Atlas): Nucleoplasm; Cytosol
Pathways (Reactome):
Disease: Dengue Virus-Host Interactions; HCMV Early Events; HCMV Late Events
Chromatin organization: HATs acetylate histones; HDACs deacetylate histones
Metabolism of proteins: Ub-specific processing proteases
Gene Ontology:
Molecular function: DNA binding; structural constituent of chromatin; protein heterodimerization activity
Biological process: antibacterial humoral response; antimicrobial humoral immune response mediated by antimicrobial peptide; chromatin organization; innate immune response in mucosa
Cellular component: extracellular exosome; nucleus; nucleoplasm; nucleosome; chromosome
Genetic constraint (gnomAD): Loss-of-function variants: 8 observed, 5.63 expected, observed/expected ratio (o/e) 1.42, 90% interval 0.8 to 1.92. That is too few expected variants to judge how well the gene tolerates losing a copy. Missense variants: 106 observed, 172.54 expected, observed/expected ratio (o/e) 0.61, 90% interval 0.52 to 0.72. Synonymous variants: 104 observed, 71.98 expected, observed/expected ratio (o/e) 1.44, 90% interval 1.23 to 1.7.
Homologues: Orthologues: chimpanzee H2BC18 (100% identical), guinea pig H2BC18 (100% identical), macaque H2BC18 (100% identical), mouse H2bc18 (100% identical), pig H2BC18 (100% identical), rabbit H2BC18 (100% identical). Paralogues in human: H2BC9 (99% identical), H2BC10 (98% identical), H2BC17 (98% identical), H2BC4 (98% identical), H2BC6 (98% identical), H2BC7 (98% identical), H2BC8 (98% identical), H2BC12 (98% identical), H2BC15 (98% identical), H2BC21 (98% identical), H2BC5 (98% identical), H2BC11 (97% identical), and 9 more.
Diseases named in the same sentence as H2BC18 in open-access papers:
H2BC18 is named in the same sentence as 12 diseases in open-access papers, as found by Europe PMC text mining. Sharing a sentence is not in itself a finding about the gene and the disease. The quoted sentences say what the papers report.
cervical squamous cell carcinoma (1 paper, 2022). A squamous cell carcinoma arising from the cervical epithelium. "In addition, H2BC18 had a hypermethylated status in germ cell tumors (GCT), cervical squamous cell carcinoma and endometrial adenocarcinoma (CSEC), and uterine carcinosarcoma (UCS)." (PMID 36387186, 2022).
H2BC18 also shares sentences with these, for which no sentence is quoted: cancer (2 papers); breast carcinoma (1); colon cancer (1); colorectal cancer (1); endometrial adenocarcinoma (1); germ cell tumor (1); prostate hyperplasia (1); renal cell carcinoma (1); systemic lupus erythematosus (1); tumor (1); uterine carcinosarcoma (1).